ZBTB45 (zinc finger and BTB domain containing 45)
Description:
May be involved in transcriptional regulation (Probable). In the central nervous system, may play a role in glial cell differentiation (By similarity).
Synonyms: ZNF499; FLJ14486
Tractability: PROTAC: its protein half-life has been measured.
Gene: Protein-coding gene on chromosome 19 (58,513,530 to 58,538,911, reverse strand). Ensembl gene ENSG00000119574.
Subcellular location: Nucleus
Subcellular location (Human Protein Atlas): Cytosol; Nuclear bodies
Gene Ontology:
Molecular function: protein binding; sequence-specific double-stranded DNA binding; DNA-binding transcription repressor activity, RNA polymerase II-specific; RNA polymerase II cis-regulatory region sequence-specific DNA binding
Biological process: negative regulation of transcription by RNA polymerase II; regulation of cytokine production; regulation of immune system process
Cellular component: nucleoplasm; nucleus
Genetic constraint (gnomAD): Loss-of-function variants: 14 observed, 23.3 expected, observed/expected ratio (o/e) 0.6, 90% interval 0.4 to 0.94. The upper end of that interval is the gene's LOEUF score, 0.94, which puts it in group 3 of 6, group 1 being the genes least tolerant of losing a copy. Missense variants: 568 observed, 631.66 expected, observed/expected ratio (o/e) 0.9, 90% interval 0.84 to 0.96. Synonymous variants: 281 observed, 276.02 expected, observed/expected ratio (o/e) 1.02, 90% interval 0.92 to 1.12.
Homologues: Orthologues: chimpanzee ZBTB45 (99% identical), macaque ZBTB45 (99% identical), pig ZBTB45 (91% identical), rabbit ZBTB45 (88% identical), mouse Zbtb45 (88% identical), rat Zbtb45 (88% identical), guinea pig ZBTB45 (77% identical), tropical clawed frog zbtb45 (50% identical), zebrafish si:dkeyp-84f3.5 (16% identical). Paralogues in human: ZBTB20 (39% identical), HIC2 (15% identical), ZBTB16 (15% identical), HIC1 (15% identical), ZBTB18 (14% identical), ZNF296 (14% identical), PRDM1 (14% identical), PATZ1 (13% identical), PRDM14 (13% identical), ZNF692 (13% identical), ZBTB42 (13% identical), ZBTB7C (12% identical), and 24 more.
Diseases named in the same sentence as ZBTB45 in open-access papers:
ZBTB45 is named in the same sentence as 3 diseases in open-access papers, as found by Europe PMC text mining. Sharing a sentence is not in itself a finding about the gene and the disease. The quoted sentences say what the papers report.
Becker muscular dystrophy (1 paper, 2022). Becker muscular dystrophy (BMD) is a neuromuscular disease characterized by progressive muscle wasting and weakness due to degeneration of skeletal, smooth and cardiac muscle. "From the identified disease-specific genes, four genes (ANK3, GALK2, ZBTB45 and PLXNA1) were previously reported to be involved in the pathogenesis of DMD and Becker Muscular Dystrophy (BMD), a milder form of DMD." (PMID 35388741, 2022).
cancer (1 paper, 2021). A tumor composed of atypical neoplastic, often pleomorphic cells that invade other tissues. "HHIPL2, XPO1, SALRNA1, ZBTB45, ANP32AP1, ACTR3BP5, LOC100129138, GPR45, and CAB39L gene deletions were associated with non-cancer subjects without FCH (p < 0.05), while RAB9BP1, LOC101928523, and MALRD1 gene deletions were related to non-cancer patients with FCH (p < 0.05)." (PMID 33431054, 2021).
ZBTB45 also shares sentences with these, for which no sentence is quoted: Obesity (1 paper).